OR5AK3P (olfactory receptor family 5 subfamily AK member 3 pseudogene)
Description:
Odorant receptor.
Synonyms: OR5AK3
Gene: Protein-coding gene on chromosome 11 (56,971,050 to 56,971,979, forward strand). Ensembl gene ENSG00000181282.
Subcellular location: Cell membrane
Homologues: Orthologues: chimpanzee OR5AK3P (95% identical), dog OR5AK7 (79% identical), mouse Or5ak24 (76% identical), rat Or5ak25 (76% identical), rat Olr440 (75% identical), rat Or5ak24 (75% identical), mouse Or5ak23 (75% identical), mouse Or5ak25 (75% identical). Paralogues in human: OR5AK2 (83% identical), OR5B12 (53% identical), OR8U3 (52% identical), OR5B21 (51% identical), OR5AP2 (51% identical), OR5P3 (50% identical), OR5B3 (50% identical), OR5AR1 (49% identical), OR5F1 (49% identical), OR5I1 (49% identical), OR5J2 (49% identical), OR8D4 (49% identical), and 84 more.